EGFR (epidermal growth factor receptor)
Diseases named in the same sentence as EGFR in open-access papers (continued):
Sharing a sentence is not in itself a finding about the gene and the disease.
tumor (continued). "Recently, a study reported on five patients experiencing hyper-progression who had NGS performed on pretreatment tumor tissue, and it confirmed CNAs in MDM2/MDM4, epidermal growth factor receptor (EGFR), and several genes located on 11q13 associated with hyper-progression." (PMID 32903763, 2020). "The patients with lower lobe cancer had a higher proportion of non-adenocarcinoma histology, a higher tumor marker level, and a lower proportion of EGFR mutations, which were also associated with an increased risk for 5-year all-cause mortality." (PMID 32913267, 2020). "The N-glycans of EGFR are involved in ligand binding, dimerization, and tumor promotion." (PMID 32260356, 2020). "Retrospective anti–EGFR-treated tumor samples from 205 patients were identified from the discovery and validation (CO.20) cohorts after clinical review and quality control of the tumor blocks and tumor-derived RNA." (PMID 33015526, 2020). "In addition, there is evidence that the release of EGFR ligands from cancer associated macrophages depends on ADAM17 and it was demonstrated that myeloid EGFR activation is a prerequisite for the release of tumour-promoting IL-6." (PMID 32698506, 2020). "However, osimertinib possessed a more potent anti-tumor efficacy than Formo in EGFR activating mutation xenografts, including HCC827, H3255, and H1975 tumors, and the tumor volume was less than 100 mm3 at the endpoint." (PMID 32276600, 2020). "However, using positive immunomagnetic selection targeting EpCAM, HER2, and EGFR improved and optimized the enrichment of tumor stem cell and EMT like CTC compared to cell capturing with anti-EpCAM alone in different tumor entities." (PMID 33014830, 2020). "Interestingly, the staining intensity of P-YB-1, P-ERK1/2, and EGFR in the normal tissue was markedly less than in the corresponding tumor tissue obtained from PT1." (PMID 33003386, 2020). "The determination of HER2 may, therefore, be of clinical utility and could be justified at least in native RAS tumours resistant to anti-EGFR treatment." (PMID 32418154, 2020). "The objective of this study was to evaluate the concordance of two commercial EGFR mutation tests: an RT-PCR method cobas EGFR mutation test v2 (cobas v2) and a PNA-based PCR method PANAMutyper R EGFR (PANAMutyper) in tumor tissue and plasma from NSCLC patients." (PMID 32224854, 2020). "The involvement of EGFR signalling in the induction of pro-tumour immune tolerance has been characterised particularly well for NSCLC, where it has been demonstrated that EGFR+ sEVs can induce differentiation of tolerogenic dendritic cells (DCs), which suppress the anti-cancer immune response." (PMID 33228060, 2020). "Activation of the EGFR pathway plays a vital role in tumor proliferation of several solid tumors." (PMID 32337094, 2020). "EGFR signaling might be compromised also by upregulation of miR-424-5p, which is a negative regulator of EGFR expression, as observed in tumor cells." (PMID 32599769, 2020). "However, in five of our 27 patients in whom we evaluated the tumor PD-L1 expression, the evaluation was conducted in tumor tissue specimens obtained after the initiation of first-line EGFR-TKI treatment." (PMID 33255696, 2020). "A possible correlation between EGFR amplification and the anti-tumor efficacy of GC1118 was observed, suggesting that EGFR amplification may be a potential biomarker for guiding treatment choices." (PMID 33142709, 2020). "It will be of interest, in future, to learn whether this distinction holds true for factors promoting tumor formation in human cancers that depend on EGFR overexpression vs. those dependent on Ras mutants." (PMID 32737065, 2020). "The majority of tumor mass was identified to be positive for EGFR and Ki-67." (PMID 33050232, 2020).
tumor (continued). "Moreover, the HPV E5 protein has also a relevant role in tumor cell invasion and metastasis for its ability to increase the expression of the epidermal growth factor receptor (EGFR) and c-MET, the latter being also critical for viral gene expression." (PMID 32154165, 2020). "The mean positive cell percentage of EGFR in 30 tumor tissues was (68.6 ± 14.7)%." (PMID 32432044, 2020). "The EGFR pathway regulates the crosstalk between tumor cells and TME." (PMID 32883032, 2020). "EGFR showed equal expression in both tumor and normal pancreatic parenchyma." (PMID 33004930, 2020). "We have identified for the first time that the lowest MAF that can be detected in an HRM assay is 0.25%, irrespective of the type of somatic mutation in EGFR gene obtained from an FFPE tumor tissue." (PMID 32962681, 2020). "Oncogenic EGFR signaling results in the expansion of an overwhelming number of AMs with an immunosuppressive phenotype, and their selective depletion results in a dramatic decrease of tumor burden." (PMID 32125091, 2020). "EGFR amplification is always accompanied by EGFR T790M, which raises the question as to whether tumor cells can amplify EGFR to promote drug resistance or to circumvent the deleterious effect of T790M." (PMID 32549388, 2020). "The findings of our study suggest that the tumor PD-L1 status is associated with the likelihood of acquisition of T790M, independent of the EGFR mutation, that is, exon 19 deletion or exon 21 L858R." (PMID 33255696, 2020). "Patients in whom tumor EGFR escapes endocytosis respond better to EGFR monoclonal antibody therapy." (PMID 32516941, 2020). "Our previous results showed that the pressure of selection exerted by BVZ induced down-regulation of the phospho tyrosine phosphatase receptor kappa (PTPRκ), a natural inhibitor of EGFR activity resulting in the acquisition of increased proliferation of tumor cells." (PMID 31938054, 2020). "Additionally, primary tumor location has a functional role as a biomarker with impact on prognosis and efficacy of EGFR-antibody-based therapy." (PMID 32449003, 2020). "Furthermore, a study on CRC HCT116 cells demonstrated that monoglyceride EPA (MAG-EPA) promotes apoptosis and inhibits tumour growth by suppression of the EGFR activation pathway." (PMID 33287803, 2020). "Further studies into anti-tumor activities against EGFR-expressing CRC cells are necessary in order to obtain a more detailed understanding of antibody therapy against CRC cells with KRAS p.G13D, which will lead to the development of more effective clinical treatments." (PMID 32839411, 2020). "In the preclinical setting, the inhibition of HSP90 could be effective against resistant tumours, such as mutant EGFR-driven lung adenocarcinoma." (PMID 32895397, 2020). "On the basis of these results, we examined whether EMab-17 exerts similar anti-tumor activities against EGFR-expressing cells, especially CRC cells." (PMID 32839411, 2020). "EGFR status is determined through a histological biopsy of the tumour." (PMID 32804306, 2020). "Combined, our chemical inhibitor screening, gene knockdown and bioinformatic analyses consistently indicate a collaborative role of the integrin-FAK pathway and BRD4/Myc-linked epigenetic network in controlling tumor cell variability in NSCLC, regardless state of KRAS or EGFR." (PMID 32793596, 2020). "Furthermore, EGFR-mutant NSCLC patients who developed resistance to EGFR-TKIs via acquisition of T790M showed lower tumor PD-L1 expression levels and also a lower proportion of patients with positive tumor PD-L1 expression." (PMID 33255696, 2020).
tumor (continued). "On the other hand, 36% of plasma samples analyzed at progressive disease were negative for EGFR mutation, indicating the possible lack of circulating tumor DNA (ctDNA)." (PMID 33520716, 2020). "The effect of anti‐PD‐1/PD‐L1 monoclonal antibody in NSCLC patients with epidermal growth factor/anaplastic lymphoma kinase (EGFR/ALK) mutation was poor, which was related to the simultaneous reduction in T effector lymphocytes in the tumor body under the influence of the mutation." (PMID 32875727, 2020). "Current developments of bispecific antibodies and CAR-T cells targeting Her2 and EGFR, respectively, have shown that tumor selectivity can be enhanced by lowering the affinity and enforcing the avidity of the antibody; thus, T cell triggering becomes only effective at high antigen density." (PMID 32504247, 2020). "Alternatively, EGFR and KRAS mutations could also exist in different subclonal mCRC populations in the same tumor, as a result of tumor heterogeneity, driving the activation of the same pathway." (PMID 32457828, 2020). "Therefore, it remains a crucial need to develop EGFR TKI-based combination therapies that can optimize tumor control and delay disease progression." (PMID 33244458, 2020). "Analysis of T cell stimulation in co-culture settings with tumor cell lines presenting different EpCAM/EGFR expression profiles demonstrated costimulatory capacity of all fusion proteins in a broad range of target expression, enhancing the effect of suboptimal bispecific antibody concentrations." (PMID 32504247, 2020). "Interestingly, the radiomic signatures in nivolumab (immunotherapy) and gefitinib (EGFR-targeted) arms were dominated by intra-tumor spatial heterogeneity and tumor-parenchyma density transition descriptors." (PMID 33473253, 2020). "Several strategies can be used to overcome tumor resistance (rechallenge, reintroduction, sequential therapy, dose intensification), and rechallenge seems to be the most promising in the context of anti-EGFR mAbs." (PMID 32825275, 2020). "EGFR levels and its activity varied from tumor to tumor, a situation that may explain the general failure to ERLO in clinical trials." (PMID 31938054, 2020). "Tumours facilitate progression by the EGFR/Ras-induced production of CCL20." (PMID 32601464, 2020). "Therefore, EGFR-targeted drugs are clinically used in a variety of cancers, and EGFR is also a hot target for tumour diagnosis and treatment." (PMID 32728182, 2020). "The nanocapsules dramatically improved the tumor accumulation of cetuximab, which bound with EGFR." (PMID 32587779, 2020). "Furthermore, the suppressive effect of krill oil extract on EGFR and pEGFR is comparable with Cetuximab, a monoclonal antibody that binds to the EGFR extracellular domain and deactivates the EGFR receptor to inhibit tumour cell growth." (PMID 33287803, 2020). "In addition, bispecific antibody targeting both Vγ9Vδ2 TCR and epidermal growth-factor receptor (EGFR) allows Vγ9Vδ2 T cells accumulation and activation specifically at the tumor sites, and kills tumor cells in vitro and in mouse xenograft model." (PMID 32413966, 2020). "High expression of miRNA-373 promoted tumor cell migration and up-regulated EGFR expression." (PMID 33162827, 2020). "Genetic fusion of TPP11 to the C-terminus of the heavy chain of an anti-EGFR antibody (designated as cetuximab-TPP11: Ctx-TPP11) improved tumor homing and tumor tissue penetration of Ctx-TPP11 by loosening cell–cell junctions, as compared to the parental antibody, cetuximab." (PMID 32560565, 2020). "In addition, the delayed development of cancer stem-like cells was accompanied with reduced tumor burden and improved recurrence free survival as well as overall survival in xenograft models of EGFR-mutant NSCLC cells." (PMID 32820157, 2020).
tumor (continued). "Notably, YTHDF2 functioned as a tumor suppressor in HCC by negatively modulating EGFR mRNA stability via its binding to the m6A site in the 3′-UTR of EGFR mRNA, in turn impairing the MEK/ERK pathway and consequently impeding the cell proliferation and growth." (PMID 33062255, 2020). "However, 5-FU treatment significantly reduced tumor size and weight in mice injected with EGFR-siRNA transfected HT29-R cells." (PMID 31896739, 2020). "Recently, primary tumor sidedness emerged as a predictive factor for response to anti-EGFR treatment; in particular, left-sided tumors would benefit from anti-EGFR mAbs, whereas right-sided tumors are considered anti-EGFR-resistant." (PMID 32413973, 2020). "This patient's paired tumor tissue also harbored EGFR G719A with a higher AF of 40.30%." (PMID 32685009, 2020). "The status of EGFR amplification correlates with the tumor’s potential to migrate." (PMID 33066251, 2020). "In this study, we found that the tumor tissue of all conjunctival SCCs (100%) expressed EGFR." (PMID 32833992, 2020). "Furthermore, relatively stronger fluorescence intensity of invasive tumor markers (cd31 and EGFR) was observed in GDCX tumor." (PMID 32050972, 2020). "Other mechanisms of PD-L1 upregulation are overexpression of Myc along with mutated KRAS; activating mutations of EGFR, KRAS or JAK2; and CMTM4 and CMTM6 posttranslational regulation in tumor cells and DCs, in addition to other posttranscriptional modifications." (PMID 33322522, 2020). "Furthermore, PIPKIγi5 is critical for the stable expression of Mig6, a tumor suppressor that directly binds to EGFR and inhibits EGFR activation." (PMID 33061794, 2020). "On one side, this may imply that coexisting EGFR and KRAS activating mutation might provide additional advantages to tumor progression in mCRC." (PMID 32457828, 2020). "High EGFR expression also leads to reduced overall survival (OS) and increased tumor recurrence." (PMID 32708604, 2020). "The EGFR is involved in survival, proliferation, tumor invasion, and tumor immune evasion." (PMID 32185612, 2020). "Finally, EGFR, classically expressed by NSCs and promoting their proliferation, is often overexpressed in GBM and has been associated with tumor initiation, tumor growth, cell invasion, angiogenesis, and resistance to chemo- and radiotherapy." (PMID 33575218, 2020). "However, the inhibitory efficacy of Formo on EGFR signaling, and the anti-tumor effect of Formo on both osimertinib sensitive and resistant NSCLC cells, is not clear." (PMID 32276600, 2020). "CARs targeting other molecules constitutively expressed on tumor cells from solid epithelial malignancies such as EGFR and HER2 may also be useful and deserve further study." (PMID 32633234, 2020). "Indeed, in preclinical studies, tumor uptake of zirconium-89 labeled cetuximab ([89Zr]Zr-cetuximab) in xenograft bearing nude mice was not only dependent on tumor EGFR expression but also on pharmacokinetic and dynamic mechanisms." (PMID 31705176, 2020). "Likewise, EGFR is frequently overexpressed or strongly activated in several tumor types and fuels tumorigenesis." (PMID 32796709, 2020). "In addition, the tumor‐bearing mice treated with the EGFR‐CAR NK cells lived longer than the mice treated with Con‐CAR NK cells." (PMID 32592435, 2020). "The contribution of Ang II-associated signals to EGFR transactivation that target LOX is supported by several mouse models, human carcinoma cell lines and human tumor tissue relevant to the pathomechanisms of AAA, vascular remodeling and hypertension, and to primary and metastatic lung carcinoma." (PMID 32708046, 2020).
tumor (continued). "Additionally, several studies found the primary tumour location to be predictive of response to anti-EGFR therapy, although only in patients with a left-sided tumour harbouring a RAS wt status." (PMID 33188279, 2020). "Tumour pathological grade and λHU in the VP were independent factors influencing the Ki-67 expression level, and smoking status and NIC in the VP were independent factors influencing EGFR mutation." (PMID 32103127, 2020). "The EGFR-dependent signaling pathways are closely related to the tumor hypoxic microenvironment." (PMID 33148251, 2020). "In bone metastases, the percentage of EGFR-positive tumour cells frequently reached 100% per tumour sample and its mean value was significantly higher than in the cohort of EGFR-positive primary tumours (92%, n = 13 vs. 58%, n = 1258; two-tailed Mann–Whitney test, p < 0.0001)." (PMID 32901137, 2020). "We also compared pT654 EGFR levels in tumors derived from the 67NR and 4T1 tumor cells." (PMID 31597954, 2020). "Tumor tissues were obtained from only 61 patients for EGFR expression assessment." (PMID 33026449, 2020). "The result indicated that IRE1α-XBP1s pathway might participate in EGFR driven tumor cell proliferation." (PMID 32489465, 2020). "It is noteworthy that EGFR-TKIs could modulate immune responsiveness to cancer by shaping the tumor microenvironment (TME) and enhancing ICIs benefit." (PMID 32760402, 2020). "Furthermore, CAFs isolated from these patient tumor tissues and cultured in vitro (confirmed to be CAFs through the expression of CAF-associated markers), also expressed EGFR." (PMID 32481658, 2020). "The correlation between NT5DC2 expression and EGFR expression in 79 HCC tumor tissues was examined." (PMID 32382041, 2020). "Some evidence reported that different EGFR SNPs, such as rs2293347 and rs2227983, were involved in tumor biological behavior, including tumor metastasis, progression, and could be affected tumorigenesis." (PMID 33680380, 2020). "This may explain why left-sided CRC with wild-type RAS demonstrates better response to EGFR inhibitors than that which occurs in patients with CRC from other primary tumor locations." (PMID 32923389, 2020). "The metabolic reprogramming mediated by the aberrant expression of EGFR, which can improve the pentose phosphate pathway and aerobic glycolysis to promote DNA repair and apoptosis resistance, is an efficient oncogenic defense mechanism of tumor cells." (PMID 32349284, 2020). "However, the distribution frequency of AURKA SNP rs6024836 did not reveal a significant difference between the entire study group and the wild-type EGFR group concerning tumor stage, TNM status, or cell differentiation condition." (PMID 33050100, 2020). "We also performed an independent screen to identify factors that could suppress EGFR-driven neoplasia." (PMID 32737065, 2020). "Recent studies have shown that tumor cell-derived exosomes play a prominent role in the pathology of tumor metastases by using tumor-signaling pathway such as caveolin-1, HIF-1a, miR-21, miR-105, miR-210, β-catenin and oncogenic kinases (e.g., mutated EGFR, RAS and MAP kinases)." (PMID 32257377, 2020). "However, upon its interaction with EGFR on tumor cells, EGF induces receptor dimerization and autophosphorylation which activate several downstream kinase cascades." (PMID 32194412, 2020). "Furthermore, knockdown of GSDMD attenuates tumor proliferation by promoting apoptosis and inhibiting epidermal growth factor receptor (EGFR)/Akt signaling axis." (PMID 33613533, 2020). "We reasoned that simultaneous and specific inhibition of PI3Kβ isoform and EGFR may lead to a sustained synergistic anti‐tumor effect also in vivo with a well‐tolerated toxicity profile." (PMID 32672423, 2020). "The use of ctDNA is approved to assess the presence of EGFR-activating mutations in advanced lung ADC patients whenever tumor tissue is not available, and to monitor EGFR TKI treatment." (PMID 32726941, 2020).